EGFR (epidermal growth factor receptor)
Diseases named in the same sentence as EGFR in open-access papers (continued):
Sharing a sentence is not in itself a finding about the gene and the disease.
cancer (continued). "Therefore, targeting the EGFR signaling pathway has been a focus of many drug development efforts in cancer therapy." (PMID 38164181, 2024). "We first benchmarked the poly(G) assay on samples from EGFR T790M familial cancer patient III-1." (PMID 39406916, 2024). "In addition, anti-miR, which blocks onco-miR, is conjugated to an aptamer targeting cancer-related membrane proteins, such as EGFR and CD133 and is used as a target anti-cancer treatment." (PMID 39407665, 2024). "Therefore, EGFR mutation detection has been approved for first-line clinical treatment of progressive EGFR-mutated NSCLC and has become routine clinical practice in most cancer centers worldwide." (PMID 38674402, 2024). "For instance, combining bevacizumab with EGFR blockers, such as neratinib, might enhance the clinical outcomes in cancer management." (PMID 38158791, 2024). "In conclusion, based on in vitro studies on and results obtained from the management of other cancers, EGFR inhibitors could lead to promising results for the management of cutaneous laSCC and mSCC." (PMID 39451404, 2024). "This reduction may potentially activate the EGFR and β-catenin signaling pathways, thereby contributing to the emergence of cancer stem-like characteristics." (PMID 39130630, 2024). "PD-1 immunotherapy is not recommended for patients with EGFR-mutant cancers, and available data suggest that immunotherapy is ineffective in patients with EGFR mutations and even presents a risk of explosive progression." (PMID 39530091, 2024). "LC17 CAFs also protected the corresponding cancer cells carrying EGFR mutations and contributed to EGFR-targeted drug (osimertinib) resistance in LCAs, which was consistent with CAF-driven EGFR inhibitor resistance." (PMID 38643164, 2024). "Furthermore, a previous study states that EGFR is a potential dual molecular target for both cancer and AD." (PMID 39273172, 2024). "Indeed, the identified peptide inhibitor successfully suppressed the STAP-2/EGFR protein interaction, EGFR stabilization, and cancer-cell growth." (PMID 38745775, 2024). "The EGFR has become one of the most popular cancer treatment targets." (PMID 38601214, 2024). "EGFR, a transmembrane glycoprotein and a member of the ErbB family of receptor tyrosine kinases, is frequently overexpressed and mutated in GBM and many other cancers." (PMID 38360888, 2024). "This feedback activation of EGFR is particularly pronounced in CRC compared to other cancers." (PMID 39684219, 2024). "Our work also uncovers a new mechanism of regulating EGFR levels in cancer." (PMID 38260423, 2024). "We then analyzed by RT–PCR the mRNA level of EGFR and of a small number of proteins involved in its activation and/or having prognostic value in cancer diseases: MMP-2 and -9; uPA; G Protein Coupled Receptor 1 (GPER1); Estrogen Related Receptor alpha (ERR-alpha); SRC; LDH-A and -B; HBEGF." (PMID 39329717, 2024). "The inhibition of IGF-1R has also been revealed to improve therapeutic response to anti-cancer agents in cancers that do not involve EGFR mutations." (PMID 38540176, 2024). "For instance, α2-6-sialylation of the epidermal growth factor receptor (EGFR) has been shown to regulate the epithelial-mesenchymal transition (EMT) of cancer cells, influence membrane retention, regulate integrin tension, and affect focal adhesion and cell motility." (PMID 39349440, 2024). "Activated EGFR pathway contributes to onset and progression in many cancers including BC." (PMID 38671389, 2024). "Treatments targeting EGFR, including tyrosine kinase inhibitors (TKIs) like gefitinib and erlotinib, as well as monoclonal antibodies such as cetuximab, are employed to combat cancers exhibiting EGFR anomalies." (PMID 38474160, 2024). "Moreover, tumors in PartIES subtypes 5 and 6 with worse survival have relatively high EGFR activities, which is an indicator of more aggressive cancer behavior and poor survival outcomes in bladder cancer." (PMID 39584699, 2024).
cancer (continued). "While irradiation alone caused comparable responses in resistant UM-SCC 10a cells, single FGFRi and FGFRi/irradiation elicited profound activations ranging from an extensive cancer adhesome restructuring to signaling cascades associated with MAPK, EGFR or PI3K/Akt." (PMID 38378518, 2024). "Additionally, peptide QRHKPREGGGSC (QRH) preferentially binds to epidermal growth factor receptor (EGFR) cancer cells." (PMID 38399272, 2024). "Additionally, 10 patients from Hunan Cancer Hospital (HNCA) were included to analyze the differences in efficiency among EGFR-sensitive subtypes under various neoadjuvant strategies." (PMID 39492582, 2024). "S1P also modulates EGFR expression in both cancer and non-cancer cells." (PMID 39723240, 2024). "Using a pathway-centered approach, our work also identified molecular mechanisms, like EMT, a non-genetically driven known mechanism of resistance to anti-cancer compounds including EGFR inhibitors, uniquely attributable to subpopulations of cancer cells less responsive to treatment." (PMID 39061010, 2024). "The EGFR is a very important gene involved in most of the cancers." (PMID 39434198, 2024). "Additionally, due to their structural similarity to known EGFR inhibitors, they were also evaluated for their anticancer activity against a panel of eight cancer cell lines." (PMID 39683709, 2024). "Studies have shown that nuclear EGFR is an indicator of poor clinical outcomes in cancer patients." (PMID 38820302, 2024). "Therefore, these organometallic conjugates hold potential for further exploration to develop more potent theranostic agents for EGFR-overexpressing cancers." (PMID 39518106, 2024). "The off-target alterations could activate signaling downstream or in parallel to the targeted EGFR protein, sustaining oncogenic pathways and favoring cancer cell survival and growth." (PMID 38764025, 2024). "Secondly, diverse downstream pathways like EGFR/MAPK, AKT/mTOR and WNT/β-catenin were involved in different cancer types, which might cause different pathological behaviors 73,99,175." (PMID 38385078, 2024). "Although the independence of synergism from EGFR increased the possibility of this result, it was still surprising since EGFR inhibitors inhibit several other RTKs in cancer cells, which would reprogram intracellular machinery, leading to distinctive dependency signatures." (PMID 39033209, 2024). "EGF stimulates EGFR to increase the production of IL-8 from cancer cells." (PMID 38673992, 2024). "Therefore, EGFR represents a potential druggable target for the development of novel targeted cancer therapies." (PMID 39564119, 2024). "As an upstream regulator of RAS, EGFR is integral to KRAS-driven cancers." (PMID 39770538, 2024). "Indeed, GBM has the highest frequency of alterations in the EGF/EGFR pathway across 33 types of human cancer." (PMID 39606019, 2024). "In general, EGFR pathways are crucial for understanding cancer mechanisms." (PMID 39063176, 2024). "However, the demonstration of these effects of gefitinib on lipid metabolism represent an intriguing insight into the potential mode(s) of action of this TKI inhibitor with relation to role of EGFR in cancer." (PMID 39048625, 2024). "Notably, curcumin, an active constituent of turmeric, has been shown to effectively impede cancer proliferation and metastasis by disrupting EGFR signaling pathways, particularly by blocking EGFR phosphorylation." (PMID 39035991, 2024). "CRIS-C cancers had elevated EGFR signalling with sensitivity to EGFR inhibitors." (PMID 38319359, 2024). "EGFR and all its downstream signaling pathways have been demonstrated to regulate autophagy, so inducing autophagy-related cell death to overcome primary resistance to anti-EGFR treatments is a reasonable strategy for cancer drug discovery." (PMID 38764025, 2024). "It would be interesting to find out whether these principles apply to cancers driven by EGFR overexpression which currently have very limited therapeutic options." (PMID 38503739, 2024).
cancer (continued). "Consequently, EGFR is one of the most significant targetable mutations in NSCLC and is widely explored in cancer research, medication development, and diagnosis." (PMID 38255882, 2024). "When combined, these findings suggest that targeting the EREG/EGFR pathways could be a strategy for cancer therapy, especially when overcoming therapeutic resistance." (PMID 38398101, 2024). "However, the combination of any EGFR TKI with an anti-CD47 antibody dramatically eliminated cancer cells and prevented development of persister cells." (PMID 38483480, 2024). "The studies indicate that silibinin could be an effective drug for inhibiting EGFR expression in cancer cells." (PMID 38504785, 2024). "In this study, we observed that cancer cells resistant to KRAS G12C inhibitors also display cross-resistance to other targeted therapies such as inhibitors of epidermal growth factor receptor (EGFR), insulin-like growth factor 1 receptor (IGF1R), MEK, PI3K, or SHP2." (PMID 39704172, 2024). "However, epidermal growth factor receptor (EGFR) is highly expressed in these triple-negative BCs and is suggested to be associated with BRCA1 mutations in this cancer subtype." (PMID 38254741, 2024). "Thus, overexpression and activating mutations accelerate the TK activity of EGFR, resulting in the activation of MAPK, PI3K/AKT, mTOR and other signaling pathway activators to promote the proliferation of cancer cells." (PMID 39470734, 2024). "Moreover, Axl homo-dimerization, EGFR homo-dimerization, and Axl-EGFR heterophilic dimerization provide a gateway to pro-invasive signaling in cancer cells and acquired resistance to conventional therapy." (PMID 39594573, 2024). "EGFR is the key regulator of various cellular events in many cancers, including in CRC." (PMID 37183661, 2024). "These clinical stage fluorescent molecular contrast agents can target cancer cells via surface receptors such as the epidermal growth factor receptor (EGFR), prostate specific membrane antigen (PSMA), and cathepsins which would provide the ability to target many different types of cancers." (PMID 38594545, 2024). "Understanding EGFR’s complex signaling dynamics is vital for creating effective cancer treatments." (PMID 38474160, 2024). "These discoveries present a potential approach for cancer treatment by targeting EGFR/HER." (PMID 39333489, 2024). "Indeed, most cancers and in vitro analyses showed sensitivity to EGFR/VEGFR targeting drugs, coherent with BUB1’s role in regulating membrane signalling." (PMID 38396175, 2024). "Then, NIR‐PIT targeting EGFR was performed on these senescent cancer cells." (PMID 38888415, 2024). "However, clinical trials targeting EGFR in TNBC have encountered challenges due to cancer genetic heterogeneity." (PMID 38338684, 2024). "In cutaneous SCC, small molecules that inhibit EGFR-activated intracellular signaling (which, we note, is overexpressed in this type of cancer) could be used." (PMID 39451404, 2024). "The therascreen EGFR RGQ PCR Kit (22300AMX01256000), approved by the PMDA, is a CDx product developed by Qiagen that detects epidermal growth factor receptor (EGFR) gene mutations in DNA samples extracted from cancer tissue." (PMID 39598157, 2024). "The presence of EGFR gene mutations in patients with MPE was significantly higher, indicating that these mutations could facilitate cancer migration to the pleural cavity." (PMID 39596989, 2024). "Similarly, a complex of cationic liposomes conjugated to MBs with a saturating payload of siRNA increased the delivery of EGFR-siRNA to carcinoma tumors." (PMID 39088581, 2024). "Many receptors are known to be overexpressed in cancer cells, like folic acid receptor (FR), transferrin receptor (TfR), or epidermal growth factor receptor (EGFR), which have been explored as docking sites for selective targeting of anticancer chemotherapeutics." (PMID 36678830, 2023).
cancer (continued). "In addition, glycosylphosphatidylinositol (GPI) anchor peptides, inherently enriched on the exosomal membrane, have been fused with anti-EGFR nanobodies to facilitate targeting to cancer cells." (PMID 37046653, 2023). "The model we developed shows that clinically deteriorated, cachectic, with inferior quality of life scores, wild‐type EGFR, and with poor prognostic predictors tend to be classified as short OS (≤90 days), showing biological plausibility, related to cancer‐induced systemic inflammation." (PMID 36161783, 2023). "Cetuximab was able to bind to EGFR and competitively inhibited the binding to the epidermal growth factor (EGF) and other ligands, which blocked the phosphorylation of EGFR induced by ligands and mitigated the activation of the signaling pathways related to cancer development." (PMID 37371712, 2023). "This review covers EGFR structure, trafficking, and altered surface expression of EGFR receptors in cancer, with a focus on how therapy targeting EGFR trafficking may aid tyrosine kinase inhibitor treatment of cancer." (PMID 37752992, 2023). "The elucidation of the resistance mechanisms of EGFR-mutated (EGFR-mt) LA can contribute to the development of therapeutic strategies to overcome ICI resistance in EGFR-mt LA and facilitate an improved understanding of ICI mechanisms in cancer immunity." (PMID 36991099, 2023). "According to several studies, the viral S protein binds to the VEGFR (Vascular Endothelial Growth Factor Receptor) and the EGFR (Epidermal Growth Factor Receptor) more frequently in GBM cells than in other types of cancer cells, contributing to their development." (PMID 37671050, 2023). "Therefore, the conjugation of Erlotinib to fluorophores and photosensitizers is an attractive strategy for the application of the resulting conjugates in the imaging and/or treatment of cancers that over-express EGFR." (PMID 41551238, 2023). "Anti-EGFR VHHs are the most frequently reported treatment in cancer using VHHs." (PMID 37746282, 2023). "Moreover, the OA analog, K73-03, was used as an effective anticancer agent that acted via targeting EGFR in pancreatic ASPC-1 cancer cells." (PMID 36982173, 2023). "In most of these cancer cells, the activation of c-Met requires EGFR and vice versa." (PMID 37611070, 2023). "Modified VLPs delivered DOX to EGFR-expressing cancer cells." (PMID 37020877, 2023). "Anti-cancer therapy by iron chelation has been shown to inhibit many cellular processes including DNA replication, mitochondrial metabolism and oncogenic signalling pathways (e.g., EGFR)." (PMID 37509712, 2023). "Recent studies have shown that second generation epidermal growth factor receptor (EGFR) inhibitors may also be used to treat KRAS-mutant cancers such as NSCLC." (PMID 36674513, 2023). "EGFR in cancer cells can be activated by two different mechanisms." (PMID 36812484, 2023). "Because cancer cells with these genetic alterations in EGFR gene become highly dependent on the continuous activation of the EGFR pathway to establish and maintain their growth advantage, EGFR has been a key target of multiple cancer therapies in clinical practice." (PMID 37766136, 2023). "Therefore, JAC4 has also proven to be potentially valuable in combination with EGFR inhibitors in cancer therapy." (PMID 37240137, 2023).
cancer (continued). "Manipulation of EGFR signaling has been proven practical to target cancer of multiple subtypes." (PMID 37305523, 2023). "The development of cancer genomics in recent decades has permitted the identification of several gene alterations as driver gene mutations for LUAD, including anaplastic lymphoma kinase (ALK), epidermal growth factor receptor (EGFR) and KRAS." (PMID 37741993, 2023). "Doing tissue and liquid NGS in parallel after EGFR‐TKI resistance may find more patients with targetable cancers." (PMID 38140788, 2023). "Notably, the prevalence of the EGFR L858R mutation is prominent in NSCLC, constituting a substantial proportion of EGFR mutations within this specific cancer category." (PMID 38273823, 2023). "Another study aimed to overcome the resistance of cancer cells to EGFR-targeting CAR-T cells." (PMID 37189725, 2023). "Moreover, in vitro EGFR inhibitory and anti-cancer activities against NSCLC cell lines in comparison with normal cell lines were studied." (PMID 37049777, 2023). "The population of Tregs in HCC (other cancers too) increased on the expression of long noncoding RNA (lncRNA), specifically the lnc-EGFR, which bound to EGFR and thereby stabilized it and sustained EGFR activation." (PMID 36768732, 2023). "In cancers, the activity of receptors—in particular, EGFR and HER2—is increased by gene amplification, mutation of the kinase or extracellular domain, and aberrant splicing contributing to several hallmarks of cancer." (PMID 37296881, 2023). "Moreover, cancer cells with high EGFR expression levels showed excellent targeting performance and good release performance, while normal cells showed low drug release." (PMID 36770595, 2023). "Consequently, the ability of nimotuzumab to counteract growth is limited due to EGFR’s kinase-independent activity, which promotes cancer cell survival." (PMID 37762316, 2023). "However, how Sia acetyl functional groups affect EGFR targeted cancer therapeutics remains unexplored." (PMID 37687086, 2023). "Thus, the effects of EGFR on Aβ, neuroinflammation, and cognitive function have spurred growing interest in the potential repurposing of EGFR inhibitors used as anti-cancer drugs for the treatment of AD." (PMID 37601068, 2023). "As a result, cetuximab effectively halts the growth and survival of EGFR-dependent cancer cells." (PMID 38136430, 2023). "Specifically, inhibitors of EGFR and other tyrosine kinases, which are multitarget enzymes, may have practical value for treating cancer and AD." (PMID 37601068, 2023). "Therefore, targeting aberrant EGFR represents an appealing strategy for EGFR-expressing cancer treatment interventions." (PMID 37623652, 2023). "EGFR has been found to be overexpressed in multiple types of cancer, including OSCC." (PMID 37623256, 2023). "In addition, using CCLE and Project Achilles data from DepMap (Cancer Dependency Map) portal, we screened for top genes correlated with EGFR dependence in the same 930 cancer cell lines." (PMID 37542131, 2023). "Stimulation of EGFR has been shown to increase activation of MMPs and ADAMs, further promoting production of sE-cad, suggesting the existence of a positive feedback loop between EGFR activation and sE-cad production, increasing cancer cell proliferation." (PMID 37760996, 2023). "Thus, determining the mechanism of resistance to osimertinib therapy remains an important challenge in EGFR-induced cancer." (PMID 37754201, 2023). "The cancer genome atlas has demonstrated that right-sided tumors display a hypermutated genotype that is largely diploid with prevalent microsatellite instability, while left-sided tumors usually contain KRAS mutations and EGFR/HER2 amplifications." (PMID 36900187, 2023). "NTSR1 regulates EGFR transactivation in several cancer cells." (PMID 37508387, 2023).